Y_RNA (Y RNA )
Gene: Miscellaneous RNA gene on chromosome 1 (185,251,313 to 185,251,411, forward strand). Ensembl gene ENSG00000201421.
Homologues: Orthologues: chimpanzee Y_RNA (100% identical). Paralogues in human: Y_RNA (93% identical), Y_RNA (92% identical), RNY3 (91% identical), Y_RNA (91% identical), RNY3P1 (90% identical), Y_RNA (90% identical), RNY3P14 (89% identical), Y_RNA (89% identical), Y_RNA (88% identical), RNY3P11 (87% identical), Y_RNA (87% identical), RNY3P16 (86% identical), and 97 more.